S100A4 (S100 calcium binding protein A4)
Diseases named in the same sentence as S100A4 in open-access papers (continued):
Sharing a sentence is not in itself a finding about the gene and the disease.
tumor (continued). "Among the numerous molecules of the tumor microenvironment that play causal roles in metastatic spread of cancer cells is the S100A4, which belongs to the S100 family of small Ca-binding proteins." (PMID 25884510, 2015). "In esophageal squamous cell carcinoma, the ability of S100A4 to promote tumor invasion and metastasis is associated with the upregulation of MMP2 and the down-regulation of E-cadherin." (PMID 25310523, 2014). "Upregulation of the metastasis-promoting S100A4 protein has been linked to tumor migration and invasion, and clinical studies have demonstrated that significant expression of S100A4 in primary tumors is indicative of poor prognosis." (PMID 25310523, 2014). "Chromosomal abnormalities and altered expression of S100A4 have been implicated in tumor metastasis." (PMID 23408941, 2013). "The combination of loss of E-cadherin and gain of S100A4 in the tumor invasive margin can be used to stratify patients with the same AJCC stage into different survival groups." (PMID 23783026, 2013). "These reviews have shown a qualitative description about the multiple roles of S100A4 protein in tumorigenesis and metastasis and the inverted association of tumour patients’ prognosis." (PMID 24188373, 2013). "Although the association of S100A4 with tumour progression has been explored in recent years, the available data have not been analysed comprehensively until now." (PMID 24188373, 2013). "Loss of E-cadherin, nuclear β-catenin, and gain of S100A4 were higher in the invasive margin than in the tumor center." (PMID 23783026, 2013). "S100A4 expression was associated with small tumor size and high degree of differentiation, and when analyzing the adenocarcinomas separately, significant inverse associations between S100A4 expression and lymph node metastasis as well as pTNM stage were found." (PMID 22853000, 2012). "Given that S100A4 in general is associated with poor prognosis and promotes metastasis in a number of tumor types, this result was rather unexpected." (PMID 22853000, 2012). "Overexpression of S100A4 has been associated with tumor malignancy as well as to metastasis, angiogenesis and chemoresitance." (PMID 20515499, 2010). "The metastasis-related protein S100A4, which is known to be produced by stroma cells, has been linked to both angiogenesis and the invasion of tumour cells as an extracellular factor." (PMID 20723242, 2010). "The third gene, S100A4, was associated with cancer pathogenesis, chromosomal rearrangements and altered expression of which have been implicated in tumor metastasis." (PMID 19874631, 2009). "S100A4 is capable of inducing metastasis in animal models and is associated with aggressive phenotype of human tumours." (PMID 16265347, 2005). "Likewise, they differ from its well-established role in tumor progression, where elevated S100a4 expression is frequently associated with enhanced proliferative capacity and increased metastatic potential." (PMID 41596498, 2026). "In addition to being expressed in tumours, upregulated S100A4 levels are linked to several pathophysiological processes that do not involve tumours." (PMID 40270992, 2025). "However, the mechanism underlying the binding of CLDN18.2 to S100A4 in the tumor microenvironment remains elusive and requires further investigation." (PMID 38200591, 2024). "Recent studies suggest that the nuclear localization of S100A4 is associated with tumor stage in CRC and may play a role in gene regulatory pathways related to metastatic phenotypes." (PMID 39205741, 2024). "Furthermore, endogenous cancer-associated fibroblast S100A4 functions to induce resistance to chemotherapeutic agents through myofibroblast transdifferentiation and resultant stiffening of the tumor stromal matrix." (PMID 38072048, 2024). "Several tumor components (cancer cells, cancer-associated fibroblasts, or immune cells) are capable of secreting S100A4, highlighting that its pro-tumorigenicity may be mediated by its inclusion in sEV cargo." (PMID 38564289, 2024).
tumor (continued). "Furthermore, S100A4 is also positively linked with the expression of PD-L1 and the inhibition of anti-tumor T cell activity." (PMID 38611008, 2024). "Finally, we found that neoadjuvant chemotherapy (NACT)/chemoradiotherapy (NCRT) can reverse the association of S100A4 with prognosis from the tumor progression-associated to favorable one." (PMID 36895491, 2023). "Thus, to investigate the cause of the increase in tumor growth in Pan02 S.C. tumors in the S100a4-Cre; Ext1f/f mice, the microarray data were analyzed." (PMID 36809261, 2023). "In the same study, a tendency toward the same evolution was observed for S100A4, while two other proteins in the S100 family, encoded by the S100a6 and S100a11 genes, exhibited a similar increase in untreated tumor-bearing rats, which was completely reversed upon curcumin treatment." (PMID 35873564, 2022). "In short, we could found from the results that, mRNA expressions of S100A4/6/10/14/16 were significantly associated with tumor grades, which may have potential value of clinical transformation." (PMID 34530774, 2021). "s100A4 is a protein known to be associated with tumor metastasis." (PMID 34885247, 2021). "In order to further evaluate the paracrine action exerted by S100A4, we sought to determine whether S100A4 may trigger biological effects on main components of tumor microenvironment as cancer-associated fibroblasts (CAFs)." (PMID 33946884, 2021). "Numerous studies have indicated that S100A4 is associated with tumor progression." (PMID 32696952, 2020). "However, publication bias was found in the association between S100A4 expression and tumor differentiation in patients with NSCLC (P=0.044 for Begg’s test; P=0.013 for Egger’s test)." (PMID 32696952, 2020). "In addition, present meta-analysis results indicated that overexpression expression of S100A4 was associated with clinicopathological characteristics, including patient’s age, tumor differentiation, LNM, TNM stage, and pathological subtype." (PMID 32696952, 2020). "Within the tumor, MSCs differentiate into S100A4-secreting cancer-associated fibroblasts (CAFs)." (PMID 31844158, 2019). "However, the exact molecular mechanisms underlying these interactions in different non-tumor pathophysiologies vary, and S100A4 is likely one of the cross-linking factors that acts as common intrinsic constituents of biological mechanisms." (PMID 29204268, 2017). "In addition to its expression in tumors, upregulation of S100A4 expression has been associated with various non-tumor pathophysiology processes." (PMID 29204268, 2017). "The protein S100A4 is closely associated with both non-tumor and tumors." (PMID 29204268, 2017). "Similar to S100A4, calcyclin is associated with the tumour progression and invasion." (PMID 26880885, 2016). "This delay in tumor growth could be caused by the suppression of the pro-angiogenic function of S100A4." (PMID 25884510, 2015). "Tumor-associated fibroblasts are one of the sources of extracellular S100A4 in tumors." (PMID 25884510, 2015). "The S100A4 protein exhibits, at least in part, its pro-metastatic function as an extracellular factor produced by stroma-associated fibroblasts that attracted T-cells to the tumor site and to the pre-metastatic lungs." (PMID 25884510, 2015). "The suppression of tumor development and metastasis in S100A4(-/-) mice was associated with a decrease in T-cell infiltration, suggesting that S100A4 could affect T-cell production in general." (PMID 25884510, 2015). "S100A4 protein is closely associated with tumor invasiveness and metastasis." (PMID 25339497, 2015). "In our previously published report we showed that S100A4, OPN and ephrin-A1 were highly expressed in NSCLC tumor tissue, and that S100A4 expression was associated with adenocarcinoma histology, as well as with small tumor size and high degree of differentiation." (PMID 24215488, 2013).
tumor (continued). "S100A4 overexpression is strongly associated with tumor aggressiveness and it is correlated with poor survival prognosis in many different cancer types such as invasive pancreatic, colorectal, prostate, breast, esophageal, gastric, and hepatocellular cancer among others." (PMID 24023743, 2013). "S100A4 protein expression is associated with patient outcome in a number of tumor types." (PMID 24379889, 2013). "The aberrant expression of EMT-related proteins was higher in the invasive margin than in the tumor center; loss of E-cadherin, 17.9% versus 31.8% (p < 0.0001), nuclear expression of β-catenin, 10.6% versus 12.5% (p < 0.0001), and gain of S100A4, 10.2% versus 15.5% (p < 0.0001), respectively." (PMID 23783026, 2013). "To further determine the role of extracellular S100A4 in increasing tumor growth, we next sought to quantify whether anti-S100A4 therapy was associated with a decreased tumor development in the M21 model." (PMID 24023743, 2013). "Recently, the role of S100A4 in tumor-associated angiogenesis as well as in EC migration has been suggested indicating that S100A4 could act in association with other angiogenic factors to achieve responses both in vitro and in vivo." (PMID 24023743, 2013). "Based on our findings that S100A4 is associated with small tumor size and a less aggressive phenotype, one might speculate that S100A4-mediated induction of ephrin-A1 could be implicated in reduced tumor growth and invasiveness in NSCLC." (PMID 22853000, 2012). "Our present results indicate that S100A4 may positively regulate tumor cell proliferation, invasion and metastasis associated with multiple molecules." (PMID 22200787, 2012). "Importantly, using wild type and S100A4-deficient mouse models, we demonstrated a substantial influence of tumor cell-derived RANTES on S100A4 release into blood circulation which ultimately increases the metastatic burden in mice." (PMID 20442771, 2010). "Although an ultimate role of RANTES as a tumor-derived factor in the promotion of a S100A4-associated pro-malignant phenotype is postulated here, determining the precise role of RANTES requires investigating the role of additional, as yet unidentified, co-factors (e.g. CSML0-CM)." (PMID 20442771, 2010). "Moreover, S100A4-deficient mice exhibit delayed tumor uptake, impaired stroma organization and suppression of metastasis." (PMID 20442771, 2010). "We explored the factors and pathways implicated in S100A4 activation in the tumor microenvironment." (PMID 20442771, 2010). "Moreover the deeper, more invasive regions of the specimens in that study were enhanced in immunocytochemically detectable S100A4, suggesting an association of higher levels of S100A4 protein with the invading regions of the tumours." (PMID 11875708, 2002). "Interestingly, S100A4, a protein recently found to be produced by LECs and to promote sprouting during tumor-associated lymphangiogenesis, emerged as one of the most strongly upregulated genes in the skin in both the cap1 and cap2 subsets and also in valve LECs." (PMID 41186588, 2026). "Therefore, ELL(C595A) mutant might promote tumour metastasis through inducing expression of metastasis-associated genes, particularly for inducing S100A4, a well-defined metastasis-promoting gene." (PMID 27009366, 2016). "S100A4 is a metastasis-associated protein which has been linked to multiple cellular events, and has been identified extracellularly, in the cytoplasm and in the nucleus of tumor cells; however, the biological implications of subcellular location are unknown." (PMID 18554396, 2008). "In tumor progression, S100A4 interacts with key signaling mediators such as EGFR and β-catenin, which are critically involved in keratinocyte differentiation and follicular proliferation." (PMID 41596498, 2026).
tumor (continued). "Subpopulation analysis indicated that several tumor cell subtypes were markedly linked to resistance, with elevated expression levels of ALDH1A1 and S100A4 in the resistant subpopulation, notably correlating with various immunological and metabolic pathways." (PMID 40093000, 2025). "The in vivo experiments demonstrated that AML cells with high S100A4 protein expression exhibited increased resistance to Ara-C resistance, and the inhibition of S100A4 protein expression enhanced the killing effect of Ara-C on AML tumor cells." (PMID 40584630, 2025). "CAFs upregulate S100A4, which induces PD-L1 in tumor cells, creating an immunosuppressive microenvironment." (PMID 40772225, 2025). "Trifluoperazine (TFP), a calmodulin antagonist originally used as an antipsychotic, has been shown to inhibit S100A4 function and block tumor cell migration and invasion in vitro and in vivo." (PMID 41404073, 2025). "This cross-cancer single-cell atlas reveals S100A4, secreted by CAFs, as a conserved mediator of PD-L1 upregulation in tumor cells, driving immunosuppression and resistance to nICT." (PMID 40772225, 2025). "In contrast, tumor development in the Vtnfl/fl S100a4‐Cre+ group was predominantly restricted to the mucosal layer." (PMID 40538300, 2025). "CX3CR1 and PD1, recognized as markers of depleted macrophages closely involved in the pro‐tumor effects of M2‐TAMs, exhibited a discernible attenuation in the Vtnfl/fl S100a4‐Cre+ group." (PMID 40538300, 2025). "Immunohistochemical validation confirmed a consistent reduction in M2‐TAMs within tumor tissues of Vtnfl/fl S100a4‐Cre+ mice." (PMID 40538300, 2025). "On the one hand, S100A4 promotes tumor progression by up-regulating mitochondrial complex I subunit NADH dehydrogenase (ubiquinone) Fe-S protein 2 to enhance invasion and metabolic reprogramming." (PMID 40853920, 2025). "Subsequently, we conducted further experiments to validate how CAF-CM cells confer immune resistance to tumor cells through the expression of S100A4." (PMID 40772225, 2025). "In summary, S100A4, secreted by CAFs, promotes PD-L1 expression on tumor cells, weakening the immune system’s ability to attack these cells and leading to poorer treatment outcomes." (PMID 40772225, 2025). "In vitro experiments demonstrated that CAF-secreted S100A4 promotes PD-L1 expression in tumor cells, uncovering a potential molecular mechanism linking S100A4 to neoadjuvant therapy resistance." (PMID 40772225, 2025). "Cancer-associated fibroblasts (CAFs) respond to extracellular S100A4, S100A8, and S100A9 by activating pro-inflammatory and pro-fibrotic signaling pathways, which enhance extracellular matrix remodeling and facilitate tumor invasion." (PMID 41404073, 2025). "In EC, multiple S100 proteins, including S100A1, S100A2, S100A4, S100A8, and S100A9, have been implicated in tumor proliferation, invasion, epithelial–mesenchymal transition (EMT), and response to chemotherapy." (PMID 41303754, 2025). "Analysis of the expression levels of ALDH1A1 and S100A4 in each tumor cell subset revealed that the chemoresistant tumor cell subset exhibited elevated levels." (PMID 40093000, 2025). "ANXA2 supports angiogenesis in specific tumor-related settings, and its expression level was positively correlated with that of Cpt1a in S100a4+ alv-macro." (PMID 40658605, 2025). "S100A4 facilitates tumor-cell migration and invasion by regulating interactions between the cytoskeleton and extracellular matrix." (PMID 39852172, 2025).
tumor (continued). "Our study identified a correlation between ALDH1A1 and S100A4 with up-regulated immune and metabolic pathways in the resistant subgroup, alongside the enrichment of certain tumor and glucose metabolism-related pathways." (PMID 40093000, 2025). "In summary, we demonstrated in vitro that S100a4+ alv-macro promotes the early malignant transformation of lung epithelial cells by secreting tumor-promoting cytokines." (PMID 40658605, 2025). "Multiple S100 proteins, including S100A2, S100A4, S100A8, and S100A9, are significantly upregulated in EC compared with those in the normal endometrium, and their expression has been linked to tumor proliferation, invasion, and progression." (PMID 41303754, 2025). "The elevated lactylation levels of ALDH1A1 and S100A4 in tumor cell subgroups from the resistant group indicate that the lactylation of these genes is significant in the development of drug resistance." (PMID 40093000, 2025). "In summary, our comprehensive investigation of the ARRGRS not only deepens the understanding of Ara‐C resistance mechanisms but also provides promising insights for targeting S100A4 to inhibit tumor growth and overcome chemotherapy resistance in AML." (PMID 40584630, 2025). "S100A4 is an important member of the S100 calcium-binding protein family and has been shown to promote tumor progression in various tumors." (PMID 39852172, 2025). "The Vtnfl/fl S100a4‐Cre+ group treated with aPD1 showed the most substantial tumor reductions, with statistically significant differences from the other groups." (PMID 40538300, 2025). "Antibody blockade of S100A4 in the same mouse model also reduced both primary tumor growth and metastatic outgrowth, with reduced T cell recruitment in the pre-metastatic niche." (PMID 40078995, 2025). "In the context of cancer, S100A4 plays an important role in polarizing macrophages towards a pro-tumor, M2-like, alternatively activated state." (PMID 40078995, 2025). "Our findings delineate a pivotal role of S100A4 secreted by CAFs, primarily by stimulating tumor cells to express PD-L1, which leads to immune escape and weakens the efficacy of neoadjuvant therapy." (PMID 40772225, 2025). "In the relma-cel study, the expression levels of tumor-associated fibroblast markers (AP, TNC, CSPG4, PDGFRA, S100A4, ASPN, STC1, and ITGAM) were higher in the patients with PR than with CR." (PMID 39858099, 2025). "The subcutaneous tumor results demonstrated that the LV-S100A4 group, which exhibited high S100A4 protein expression, exhibited the largest tumor volume, the fastest growth rate, and the heaviest weight." (PMID 40584630, 2025). "In parallel, CDCP1-high tumor cells condition fibroblasts toward a myofibroblastic, pro-tumor phenotype (α-SMA, FAP, PDGFRβ, S100A4 upregulation), linking a tumor-intrinsic epigenetic program to stromal reprogramming." (PMID 41301830, 2025). "Specifically, ALDH1A1 exhibited reduced expression in the tumor group, whereas S100A4 levels were increased in the tumor group." (PMID 40093000, 2025). "These seemingly contradictory observations suggest a biphasic role for S100A4 in lung carcinogenesis - acting as a tumor progression inhibitor during early disease stages while facilitating metastatic dissemination in advanced tumors." (PMID 40853920, 2025). "HE staining further confirmed a decrease in tumor infiltration depth across the treated groups, with the Vtnfl/fl S100a4‐Cre++aPD1 group showing the most profound therapeutic effect." (PMID 40538300, 2025). "Then we aimed to figure out the contribution of Cpt1a to angiogenesis and pro-tumor function in S100a4+ alv-macro." (PMID 40658605, 2025).